FOXP4 (forkhead box P4)
Description:
Transcriptional repressor that represses lung-specific expression.
Synonyms: FLJ40908; hFKHLA
Tractability: PROTAC: UniProt records ubiquitination sites on it; ubiquitination databases record sites on it.
Gene: Protein-coding gene on chromosome 6 (41,546,363 to 41,602,384, forward strand). Ensembl gene ENSG00000137166.
Subcellular location: Nucleus
Subcellular location (Human Protein Atlas): Nucleoplasm; Cytosol
Gene Ontology:
Molecular function: protein binding; DNA-binding transcription factor activity, RNA polymerase II-specific; DNA-binding transcription repressor activity, RNA polymerase II-specific; RNA polymerase II cis-regulatory region sequence-specific DNA binding; DNA-binding transcription factor activity; sequence-specific DNA binding
Biological process: negative regulation of DNA-templated transcription; regulation of transcription by RNA polymerase II; negative regulation of transcription by RNA polymerase II; regulation of DNA-templated transcription
Cellular component: cytosol; nucleoplasm; nucleus; transcription regulator complex; chromatin
Genetic constraint (gnomAD): Loss-of-function variants: 25 observed, 70.43 expected, observed/expected ratio (o/e) 0.35, 90% interval 0.26 to 0.5. The upper end of that interval is the gene's LOEUF score, 0.5, which puts it in group 2 of 6, group 1 being the genes least tolerant of losing a copy. Missense variants: 785 observed, 858.08 expected, observed/expected ratio (o/e) 0.91, 90% interval 0.86 to 0.97. Synonymous variants: 415 observed, 376.53 expected, observed/expected ratio (o/e) 1.1, 90% interval 1.02 to 1.2.
Homologues: Orthologues: macaque FOXP4 (99% identical), chimpanzee FOXP4 (98% identical), pig FOXP4 (96% identical), dog FOXP4 (95% identical), guinea pig FOXP4 (93% identical), rat Foxp4 (93% identical), mouse Foxp4 (92% identical), tropical clawed frog foxp4 (72% identical), zebrafish foxp4 (71% identical). Paralogues in human: FOXP2 (61% identical), FOXF2 (13% identical), FOXI1 (11% identical).
Diseases named in the same sentence as FOXP4 in open-access papers:
FOXP4 is named in the same sentence as 67 diseases in open-access papers, as found by Europe PMC text mining. Sharing a sentence is not in itself a finding about the gene and the disease. The quoted sentences say what the papers report.
COVID-19 (21 papers, 2021 to 2025). A disease caused by infection with severe acute respiratory syndrome coronavirus 2. "Genome-wide association studies have identified multiple genetic variants associated with COVID-19 severity, including a robust association between the Forkhead Box P4 gene (FOXP4) and long COVID risk." (PMID 40909786, 2025). "Even assuming this stronger relationship between COVID-19 hospitalization and long COVID, the observed effect of the FOXP4 variant on long COVID still exceeds what would be expected based on the association with severity alone." (PMID 40399555, 2025). "Our colocalization analysis demonstrated the FOXP4 association identified here as the same association identified for COVID-19 severity (posterior probability > 0.97)." (PMID 40399555, 2025). "Overall, our study elucidates genetic risk factors for long COVID, the relationship between long COVID and severe COVID-19, and finally possible mechanisms of how FOXP4 contributes to the risk of long COVID." (PMID 40399555, 2025). "Our study found a possible association between MX1 and FOXP4 polymorphisms and the severity of COVID-19." (PMID 38429664, 2024). "While rs2477820 is a novel risk variant within the FOXP4 gene, it has a moderate LD (r2 = 0.295) with rs2496644, which has been linked to COVID-19 hospitalization." (PMID 39361370, 2024). "The FOXP4 variant, rs9367106, was strongly associated with both long COVID and severe COVID-19 outcomes." (PMID 37953922, 2023). "Among them, the rs1886814 of the FOXP4 gene associated with the severity of COVID-19, colocalized with a lung-specific eQTL leading to an increased FOXP4 expression." (PMID 35618891, 2022). "For instance, a variant that was identified close to FOXP4 and correlated with COVID-19 severity has a frequency that is largely variable between different populations." (PMID 35360730, 2022). "Collectively, our association analyses highlighted six common variants identified in previous GWAS or by the HGI—in/near LZTFL1, MHC, DPP9, IFNAR2, RPL24 and FOXP4—that are associated with COVID-19 as well as disease severity among cases." (PMID 35241825, 2022). "A genome-wide association meta-analysis of approximately 49,000 COVID-19 patients identified a significant association between the FOXP4 locus and severe COVID-19 disease." (PMID 34938288, 2021). "In addition, the first genome-wide significant association for the post-COVID-19 condition was for the FOXP4 locus, previously associated with COVID-19 severity, lung function, and cancers." (PMID 40076669, 2025). "The FOXP4 gene is expressed in the lung and the genetic variants associated with long COVID are also associated with differential expression of FOXP4 and with lung cancer and COVID-19 severity." (PMID 40399555, 2025). "Furthermore, variants in the FOXP4 region have also been identified as risk factors for COVID-19 hospitalization, colocalizing with FOXP4 expression eQTL in the COVID-19 HGI meta-analyses and follow-up studies." (PMID 40399555, 2025). "In conclusion, our study found that the MX1 gene promoter variant tended to be associated with a reduced risk of developing severe COVID-19 in males, and the polymorphisms near FOXP4 were significantly associated with increased COVID-19 severity in the Guangdong population." (PMID 38429664, 2024). "FOXP4 rs1886814 CC genotype (P = 0.001, OR = 3.747, 95%CI = 1.746–8.043) and rs2894439 GA + AA genotype (P = 0.001, OR = 5.703, 95% CI = 2.045–15.903) were correlated with increased risk of severe COVID-19." (PMID 38429664, 2024). "First, distinguishing whether the identified SNP or FOXP4 itself is more linked to severe COVID-19 or long COVID posed a challenge due to the distinct clinical profiles of two COVID phenotypes." (PMID 37953922, 2023). "The most significant replication was observed at FOXP4, as expected from its higher allele frequency in East Asian people than in Europeans3 (odds ratio = 1.29, 95% confidence interval 1.13–1.46, P = 9.1 × 10−5 for severe COVID-19)." (PMID 35940203, 2022).
COVID-19 (continued). "Furthermore, FOXP4 expression in both alveolar and immune cells in the lung, and the association with severe COVID-19 and pulmonary diseases such as cancer, suggests that FOXP4 may participate in local immune responses in the lung." (PMID 40399555, 2025). "However, the results pose an interesting question of whether the mechanism of FOXP4 association with long COVID is the same mechanism that contributes to COVID-19 severity." (PMID 40399555, 2025). "In addition, genetic variants in FOXP4 were associated with severe COVID-19 based on European." (PMID 38429664, 2024). "A recent genome-wide association study of long COVID-19 has revealed a significant association between a single nucleotide polymorphism located in the FOXP4 locus (chr6) and an increased risk of long COVID-19, implying that individuals may be genetically predisposed to its development." (PMID 37894116, 2023). "Earlier research has suggested that COVID-19 severity is a risk factor for long COVID8,37–39 and FOXP4 variants have earlier been implicated in COVID-19 severity." (PMID 40399555, 2025). "We replicated two loci identified by the HGI for COVID-19 severity: the LZTFL1/SLC6A20 locus on chromosome 3 and the FOXP4 locus on chromosome 6 (the latter with a variant significant at P < 5E-8)." (PMID 38517939, 2024). "Genome-wide significant associations with COVID-19 hospitalizations were found on chromosome 2 (within BAZ2B), chromosome 3 (within LZTFL1), chromosome 6 (within FOXP4), and chromosome 11 (within DDIAS)." (PMID 39361370, 2024). "Nine loci were associated with an increased risk of developing severe COVID-19 symptoms, including variants in DPP9 (OR 1.29, p = 2.0 × 10−12) and FOXP4 (OR 1.2, p = 6.0 × 10−13) that were previously shown to increase the risk for interstitial lung disease." (PMID 35618891, 2022). "Association of rs9367106 with PCC for developing persistent symptoms over COVID-19 critical illness mediated by rs1886814 may require additional involvement of altered FOXP4 function or other genes." (PMID 40724930, 2025). "We discovered an association of FOXP4 with long COVID, independent of its previously identified association with severe COVID-19." (PMID 40399555, 2025). "In summary, our findings indicate that FOXP4 is indeed implicated in lung cancer, but the long COVID and severe COVID-19 risk SNP rs9367106 does not exhibit an association with lung cancer." (PMID 37953922, 2023). "Similarly, genetic variants in SFTPD (rs721917), SLC22A31 (rs117169628), FOXP4 (rs41435745), and MUC5B (rs35705950), which are all related to lung function and lung diseases, have been significantly associated with COVID-19 severity." (PMID 35360730, 2022).
prostate carcinoma (11 papers, 2012 to 2024). A carcinoma that arises from epithelial cells of the prostate gland. "FOXP4 gene was closely associated with prostate cancer risk and is suggested a poor prognostic factor in colorectal cancer and osteosarcoma." (PMID 36203616, 2022). "The FOXP4 gene is located at chromosome region 6p21, which region was also ever linked to prostate cancer." (PMID 22662242, 2012). "We verified whether circABCC4 promotes prostate cancer progression via the circRNA–miRNA–mRNA axis by knocking down FOXP4 expression in circABCC4‐ and miR‐1182‐deficient PC3 and DU145 cells and conducting functional assays." (PMID 31270953, 2019). "Furthermore, FOXP4 gene was closely associated with prostate cancer risk in Chinese men and also long non-coding RNA FOXP4-AS1 is suggested a poor prognostic factor in colorectal cancer and osteosarcoma." (PMID 31815635, 2019). "In addition, we found that circABCC4 promotes prostate cancer progression through FOXP4 because FOXP4 overexpression in circABCC4‐deficient cells could rescue the proliferation, migration and invasion defect of circABCC4‐deficient cells." (PMID 31270953, 2019). "circABCC4 accelerated the malignant behavior of prostate cancer by sponging miR-1182 to upregulate FOXP4 expression." (PMID 39469202, 2024). "CircABCC4 expression appears to be positively correlated with FOXP4 expression in prostate cancer tissues, further indicating that circABCC4 regulates FOXP4 expression." (PMID 31270953, 2019). "Taken together, our findings indicated that circABCC4 facilitates the malignant behaviour of prostate cancer by promoting FOXP4 expression through sponging of miR‐1182." (PMID 31270953, 2019). "From the results above, we can confirm that circABCC4 and FOXP4 are overexpressed whereas miR‐1182 is down‐regulated in prostate cancer." (PMID 31270953, 2019). "The results thus far show that circABCC4 promotes prostate cancer progression through miR‐1182 and FOXP4 and that FOXP4 is a target of miR‐1182." (PMID 31270953, 2019). "We found that circABCC4 was remarkably up‐regulated in prostate cancer tissues and cell lines and promoted FOXP4 expression by sponging miR‐1182 in prostate cancer cells." (PMID 31270953, 2019). "CircABCC4 mechanically sponges miR‐1182 expression, resulting in the up‐regulation of FOXP4 and prostate cancer progression." (PMID 31270953, 2019). "Our results provide further support for association of the C2orf43, FOXP4, GPRC6A and RFX6 genes with prostate cancer in Eastern Asian populations." (PMID 22662242, 2012). "Next, we sought to discover whether circABCC4 promotes prostate cancer progression through miR‐1182/FOXP4 signalling." (PMID 31270953, 2019). "As expected, FOXP4 expression was elevated in prostate cancer tissues." (PMID 31270953, 2019). "The circRNA also promotes prostate cancer progression through FOXP4 because FOXP4 overexpression could rescue the progression defect mediated by circABCC4 deficiency." (PMID 31270953, 2019). "The related genes, C2orf43, FOXP4, GPRC6A and RFX6, are warranted for further efforts to determine the functional variations and finally to clarify the genetic mechanism of susceptibility to prostate cancer." (PMID 22662242, 2012). "Thus, circABCC4 promotes prostate cancer progression through miR‐1182/FOXP4 signalling." (PMID 31270953, 2019). "Almost all of the FOX genes were differentially expressed in prostate cancer, prostate carcinoma, and metastatic prostate cancer, except FOXA3, FOXB2, FOXC2, FOXI2, FOXI3, FOXP4, and FOXR1." (PMID 36292640, 2022). "We successfully replicated the association of rs13385191 (located in the C2orf43 gene, P = 8.60×10−5), rs12653946 (P = 1.33×10−6), rs1983891 (FOXP4, P = 6.22×10−5), and rs339331 (GPRC6A/RFX6, P = 1.42×10−5) with prostate cancer." (PMID 22662242, 2012).
lung cancer (8 papers, 2016 to 2025). A malignant neoplasm involving the lung. "FOXP4 encodes a transcription factor associated with neurodevelopmental disorders and lung cancer." (PMID 38429664, 2024). "However, it is noteworthy that 20 SNPs located within the gene body of FOXP4 displayed suggestive associations with lung cancer (Ps < 5 × 10−4)." (PMID 37953922, 2023). "Additionally, we compared the association signals around the FOXP4 gene in the self-reported lung cancer GWAS with those from the severe COVID-19 GWAS of European samples and the long COVID GWAS, which includes individuals of mixed ancestries." (PMID 37953922, 2023). "However, because FOXP4 has been reported to be linked to lung cancer, it remains uncertain whether the long COVID risk SNP is also connected to lung cancer." (PMID 37953922, 2023). "In conclusion, the observation of these SNPs displaying distinct eQTL patterns in different tissues suggests that diverse genetic elements within FOXP4 specifically contribute to COVID or lung cancer by influencing FOXP4 expression across different tissues." (PMID 37953922, 2023). "Exosomal miR-3180-3p suppresses lung cancer proliferation and metastasis by targeting forkhead box P4 (FOXP4)." (PMID 36612314, 2023). "Previous studies have also demonstrated that FOXP4 is overexpressed in non‐small cell lung cancer and modulates tumor cell growth, thereby indicating that FOXP4 may function as an oncogene." (PMID 31270953, 2019).
osteosarcoma (8 papers, 2018 to 2024). A usually aggressive malignant bone-forming mesenchymal neoplasm, predominantly affecting adolescents and young adults. "Other direct targets of miR-491-5p have been identified in osteosarcoma cells, such as FOXP4 and PKM2 (encoding forkhead-box P4 and pyruvate kinase muscle 2, respectively)." (PMID 35337159, 2022). "Of note, miR-338-3p, miR-491–5p and miR-138 were downregulated in HCC, osteosarcoma and non-small lung cancer cells, targeting FOXP4." (PMID 31815635, 2019). "Another major influence on the onset and progression of osteosarcoma is the modified frailty index 2 (MFI2), which MMFI2 promotes the proliferation and migration of osteosarcoma cells by regulating the expression of forkhead box P4 (FOXP4)." (PMID 39015175, 2024). "In addition, some potential downstream genes of miR-30b-3p, such as ATG5, PAK1, FOXP4, and MYO10 also exerted crucial roles in osteosarcoma." (PMID 35123530, 2022). "In addition, lncRNA MALAT1 and SNHG12 promoted proliferation of multiple myeloma and glioma targeting FOXP1, while lncRNA UFC1 and 7SL enhanced proliferation of cervical cancer and osteosarcoma, targeting FOXP3 and FOXP4, respectively." (PMID 31815635, 2019). "Moreover, MFI2 seems to regulate Forkhead box P4 (FOXP4), thus promoting proliferation and migration of osteosarcoma cells." (PMID 29657304, 2018).
renal carcinoma (8 papers, 2019 to 2022). A carcinoma arising from the epithelium of the renal parenchyma or the renal pelvis. "For instance, circ-ZNF609 works as a ceRNA to control FOXP4 expression by means of binding to miR-138-5p in renal carcinoma." (PMID 33256799, 2020). "In addition, circRNA ZNF609 was found to regulate fork head box P4 (FOXP4) expression by targeting miR-138-5p in renal carcinoma." (PMID 33436040, 2021). "Circ-ZNF609 promoted the development of renal carcinoma by the miR-138-5p/FoxP4 axis." (PMID 34898474, 2021). "For example, circRNA ZNF609 functions as a competitive endogenous RNA to regulate FOXP4 expression by sponging miR-138-5p in renal carcinoma.CircRNA MYLK binds to miR-29a and promotes epithelial-mesenchymal transition and xenograft growth, angiogenesis, and metastasis of bladder cancer." (PMID 30736838, 2019). "FOXP4 (Forkhead box P4) majorly reported in many cancers, is also regulated by circ-ZNF609 through sponging mir-138-5p in renal carcinoma, resulting in the downregulation of cell proliferation and invasion processes." (PMID 35223470, 2022). "By targeted binding to miR-138-5p, circ-ZNF609 upregulated the expression of the transcription factor forkhead box P4 (FOXP4) and promoted the proliferation, migration, and invasion of renal cancer cells." (PMID 35938040, 2022).
breast cancer (7 papers, 2015 to 2026). A primary or metastatic malignant neoplasm involving the breast. "For instance, IKZF3 and STAT5A overlap in immune-related pathways, while FOXP4 exhibits some distinct enrichment patterns associated with breast cancer, suggesting potential cooperative and specialized regulatory mechanisms." (PMID 40923764, 2025). "Notably, circular RNA SHKBP1 was upregulated in malignant glioma targeting FOXP1 or FOXP2, while circular RNA ZNF609 and MYO9B were upregulated in renal cancer and breast cancer, respectively, targeting FOXP4." (PMID 31815635, 2019). "While hsa-miR-3184-5p has not yet been linked to endometriosis, it exerts tumor-suppressive effects in ovarian and breast cancers via modulation of XBP1/AKT/STAT3, FOXP4, and EMT-related signalling." (PMID 41501788, 2026). "Another significant result of this study revealed that FOXP3 expression predicted the breast cancer cells’ response to anticancer drugs, whereas FOXP1, FOXP2 and FOXP4 did not predict." (PMID 35614183, 2022).
non-small cell lung carcinoma (7 papers, 2015 to 2025). A group of at least three distinct histological types of lung cancer, including non-small cell squamous cell carcinoma, adenocarcinoma, and large cell carcinoma. "FOXP4 plays a critical role in lung and brain development, and the other FOXP4 mutations are associated with non-small cell lung carcinoma and adenocarcinoma through the FOXP4-SOX2 axis." (PMID 40724930, 2025). "In contrast, it inhibits proliferation and metastasis in non-small cell lung cancer by targeting FOXP4, while the long non-coding RNA SNHG17 suppresses its tumor suppressor function in HCC." (PMID 37041584, 2023). "FOXP4 is also expressed in CD4+ and CD8+ T cells and appears to contribute to cytokine production and memory T cell responses, and a recent study reported FOXP4 as an important regulator of non-small cell lung cancer cells." (PMID 28521775, 2017). "While it thus remains to be tested if FOXP4 controls Wnt signaling as well, a separate study revealed that FOXP3 increases Wnt activity in non-small cell lung cancer (NSCLC)." (PMID 34298659, 2021).
hepatocellular carcinoma (5 papers, 2019 to 2024). A malignant tumor that arises from hepatocytes. "Interactions between FOXP proteins and various signaling pathways underscore the critical role of FOXP4 in the pathogenesis of hepatocellular carcinoma, breast cancer, medulloblastoma, and osteosarcoma." (PMID 38740744, 2024). "While FOXP4 functions as a tumor suppressor in kidney cancer, it acts as an oncogene in hepatocellular carcinoma." (PMID 38740744, 2024). "Functionally, Foxp4 was found to promote proliferation, migration, and invasion of hepatocellular carcinoma (HCC) cells in laboratory settings." (PMID 39513116, 2024).